MIR451B (microRNA 451b)
Synonyms: hsa-mir-451b
Gene: MicroRNA gene on chromosome 17 (28,861,371 to 28,861,438, forward strand). Ensembl gene ENSG00000283364.
Gene Ontology:
Biological process: miRNA-mediated post-transcriptional gene silencing